BDNF (brain derived neurotrophic factor)
Diseases named in the same sentence as BDNF in open-access papers (continued):
Sharing a sentence is not in itself a finding about the gene and the disease.
alcohol use disorder (36 papers, 2013 to 2026). "We identified a small ensemble of BDNF-positive neurons in the mouse ventrolateral orbitofrontal cortex (vlOFC), a region implicated in alcohol use disorder (AUD), that extend axonal projections to the DLS, which is associated with alcohol drinking behaviors." (PMID 41207892, 2026). "Graphical abstract of the meta‐analysis conducted to examine the role of BDNF SNPs (rs6265, rs16917204, rs7103411, rs11030104) in the risk of alcohol use disorder." (PMID 40021949, 2025). "A logistic regression analysis of the BDNF gene polymorphisms as risk factors for alcohol use disorder, with correction for age and gender." (PMID 40767639, 2025). "The growth factor brain-derived neurotrophic factor (BDNF) has been implicated in alcohol use disorder." (PMID 37372084, 2023). "Polymorphisms within the BDNF gene are correlated with susceptibility toward addictive behaviors, including alcohol abuse and chronic pain phenotypes." (PMID 34803772, 2021). "Unequivocal experimental and clinical evidences, causally linked alterations of BDNF signaling with the pathophysiology of alcohol abuse." (PMID 26501066, 2014). "In subjects with a family history of alcohol abuse over several generations, an interaction was detected between allele variants of BDNF genes associated with increased volumes of brain gray substance and the addictive behaviour." (PMID 25408911, 2013). "Brain-derived neurotrophic factor (BDNF) has been implicated in alcohol use disorder." (PMID 37372084, 2023). "Human studies show that decreased serum BDNF levels in alcoholics are associated with alcohol withdrawal symptoms, and BDNF gene polymorphisms have been linked to increased susceptibility to alcohol abuse." (PMID 27303256, 2016). "We examined whether the BDNF p.Val66Met polymorphism interacts with childhood trauma to predict alterations in brain volume in adolescents with alcohol use disorders (AUDs)." (PMID 25510982, 2014). "By identifying those HIV-infected individuals at risk for ART failures, such as those with thrombocytopenia, alcohol abuse, and with BDNF and serotonin deficits the study may permit early clinical follow-ups and interventions." (PMID 26491607, 2014). "BDNF also plays a role in sleep disturbances associated with alcohol abuse." (PMID 25408911, 2013). "Therefore, the aim of this investigation was to determine whether the BDNF p.Val66Met polymorphism interacts with levels of childhood trauma, and alcohol use disorders (AUD) to result in alterations in brain volume in a cohort of adolescents." (PMID 25510982, 2014). "Human studies support these findings, showing significantly decreased plasma BDNF concentrations in abstinent alcohol use disorder patients compared to healthy controls." (PMID 40767639, 2025). "BDNF signaling in the dorsolateral striatum (DLS) is part of an endogenous pathway that protects against the development of alcohol use disorder (AUD)." (PMID 39868120, 2025). "Further studies are needed to understand the relationship between BDNF, severity (or staging), and prognosis in alcohol use disorders, since this topic is of pivotal importance for clinical practice as well as for scientific research." (PMID 34060728, 2022). "7,11 Of note, our results also suggest that the presence of family history of alcohol use disorder contributes to the variation in BDNF levels during abstinence, perhaps due to genetic influence." (PMID 34060728, 2022). "In this sense, our main goal was to evaluate the variation of BDNF levels before and after alcohol withdrawal in individuals with alcohol use disorder during an inpatient treatment program." (PMID 34060728, 2022). "Within the subjects with mental illness, individuals with a history of drug and/or alcohol abuse showed lower levels of BDNF mRNA in layer VIb of the ITG (33% P<0.04)." (PMID 24802307, 2014). "Other than expected, the levels of NT3 and to a lesser extent BDNF levels, were found to be significantly increased in acute alcohol abuse." (PMID 25408911, 2013).
alcohol use disorder (continued). "•Alcohol Use Disorders patients exhibit lower BDNF level in serum than controls." (PMID 39430530, 2024). "The expression of BDNF related to alcohol use disorder has been actively studied in the mPFC." (PMID 39539942, 2024). "Dietary fibers intervention with inulin (found notably in onion, chicory, banana, garlic, Jerusalem artichoke and leek) in alcohol use disorder patients improves sociability score and increases circulating levels of brain derived neurotrophic factor (BDNF) during withdrawal." (PMID 37360297, 2023). "Our findings reinforce the role of BDNF as a neurotrophin involved in alcohol use disorder." (PMID 34060728, 2022). "As a corollary, it appears that BDNF plays a pivotal role in the mechanisms governing alcohol abuse and suggests that modulators of BDNF signaling could be developed as treatments to prevent a pathological use of alcohol." (PMID 35098038, 2017). "Data indicated that mood and BDNF were independent predictors of alcohol use disorders." (PMID 26501066, 2014). "The BDNF mRNA expression in the Striatum Dorsalis depends on the duration of alcohol abuse." (PMID 25408911, 2013). "Therefore, it has been speculated, that the administration of BDNF could protect against alcohol abuse." (PMID 25408911, 2013). "But not only psychical influences and the severity or form of alcohol abuse may be important for the neurotrophin expression, but also the metabolic status: for example, BDNF concentrations were found to be influenced by glucose intolerance in alcoholic patients." (PMID 25408911, 2013). "Brain‐derived neurotrophic factor (BDNF) and personality traits play a crucial role in the development of alcohol use disorder (AUD)." (PMID 40767639, 2025). "This preliminary study evaluates, for the first time, BDNF mRNA expression in leukocytes and its relationship to FAB scores in crack-cocaine and alcohol use disorder patients." (PMID 32508693, 2020). "BDNF mRNA expression in control subjects (CONT, n = 11), crack-cocaine use disorder (CUD, n = 10) and alcohol use disorder (AUD, n = 12) patients." (PMID 32508693, 2020). "In this study we investigated the BDNF mRNA expression in peripheral blood lymphocytes of crack-cocaine use disorder (CUD) and alcohol use disorder (AUD) patients, after drug detoxification treatment, using a real-time PCR approach and examining its association to FAB performance." (PMID 32508693, 2020). "Further evidence of a role for CeA BDNF in alcohol use disorders has been demonstrated by innate differences in BDNF expression between alcohol-preferring (P rats) and non-preferring rats, with P rats having naturally lower BDNF levels within the medial temporal lobe." (PMID 32369970, 2020).
endothelial dysfunction (36 papers, 2011 to 2026). In vascular diseases, endothelial dysfunction is a systemic pathological state of the endothelium (the inner lining of blood vessels) and can be broadly defined as an imbalance between vasodilating and vasoconstricting substances produced by (or acting on) the endothelium. "Changes in BDNF levels are linked to the endothelial dysfunction, a crucial early step in atherosclerotic development." (PMID 39355615, 2024). "One mechanism by which endothelial dysfunction can contribute to neurodegeneration is through impaired neurogenesis and loss of the neurotrophic and neuroprotective effects of endothelial BDNF." (PMID 37238700, 2023). "Mature brain-derived neurotrophic factor (BDNF) plays a protective role against high-glucose treatment-caused endothelial dysfunction via inducing BNIP3-mediated mitophagy." (PMID 36605901, 2022). "Our data on the association between BDNF and vWF support endothelial dysfunction as an important determinant of low BDNF levels in stable CAD patients." (PMID 29409455, 2018). "These could include a genetic predisposition like the BDNF gene polymorphism, an imbalance of proangiogenic and antiangiogenic factors, or an endothelial dysfunction with oxidative stress." (PMID 37685270, 2023). "According to this hypothesis, endothelial dysfunction and low BDNF levels could be considered the cause and effect of each other." (PMID 38137853, 2023). "However, previous observations that BDNF preserves from endothelial dysfunction and that low BDNF levels are associated with high von Willebrand Factor levels, support the re-equilibrating effect as more likely." (PMID 34205863, 2021). "First, decreased BDNF levels reduce endothelial cell survival and affect angiogenesis, which suggested that endothelial dysfunction and low BDNF levels may interact and act as both cause and effect." (PMID 29409455, 2018). "However, BDNF may have value in biological phenotyping and risk stratification by reflecting platelet activation, endothelial dysfunction, inflammatory signaling, and remodeling processes after ACS." (PMID 42123409, 2026). "Animal models of DM and hypertension demonstrate reduced neuronal and endothelial BDNF expression, which is considered a marker of endothelial dysfunction." (PMID 37238700, 2023). "By making use of the gain- and loss-of-function approaches, we observed that ANRIL mediated endothelial dysfunction through BDNF downregulation." (PMID 35906216, 2022). "Then our study provides evidence to demonstrate that ANRIL mediated endothelial dysfunction through BDNF downregulation." (PMID 35906216, 2022). "All these data demonstrated that ANRIL plays an important role in mitochondrial injury and endothelial dysfunction through recruiting EZH2 to the promoter region of BDNF." (PMID 35906216, 2022). "Another important factor that relates endothelial dysfunction to patients with RA is brain-derived neurotrophic factor (BDNF)." (PMID 33435178, 2021). "This interaction suggests that BDNF levels decrease in the context of endothelial dysfunction and OSA." (PMID 35127775, 2021). "The connection with endothelial dysfunction is also supported by the observation, that circulating BDNF level inversely correlates with vascular cell adhesion molecule-1, which is an accepted biomarker of endothelial dysfunction." (PMID 30767081, 2019). "One important finding of our study is that patients with low BDNF levels exhibited increased vWF levels, which potentially reflects endothelial dysfunction." (PMID 29409455, 2018). "Hypothetical mechanisms of RCVS involve endothelial dysfunction and sympathetic overactivity, both of which were reported to be related to brain-derived neurotrophic factor (BDNF)." (PMID 21437208, 2011). "In addition, inhibition of the expression of a brain-derived neurotrophic factor due to low-grade inflammatory conditions and endothelial dysfunction can mediate progressive neurological dysfunction." (PMID 36839420, 2023).
endothelial dysfunction (continued). "These suggested that ANRIL may be associated with endothelial dysfunction in patients with CKD, and BDNF could play an important role in this process." (PMID 35906216, 2022). "In addition, endothelium is involved in synthesis and secretion of BDNF; therefore, endothelial dysfunction leading to disturb cell signaling cascades." (PMID 34386515, 2021). "Since it has been suggested that neurocognitive deficits and endothelial dysfunction as seen in children with OSA are linked, BDNF could play an important role in this association." (PMID 35127775, 2021). "Cumulating data suggest the connection between endothelial dysfunction and BDNF as well." (PMID 30767081, 2019). "Furthermore, our study explored a novel mechanism by which metformin improves HG-induced endothelial dysfunction through the BDNF pathway." (PMID 30459620, 2018). "Physical exercise appears to mitigate endothelial dysfunction and vascular wall inflammation, and enhances neural substrates brain-derived neurotrophic factor (BDNF) and insulin growth factor-1 (IGF-1) that maximize the effects of subsequent cognitive stimulation." (PMID 29580264, 2018). "Therefore, we investigated the cerebral BDNF pathway, either neuronal or endothelial, in rheumatoid arthritis (RA) that combines both endothelial dysfunction (ED) and impaired cognition." (PMID 29375397, 2017). "Furthermore, endothelium is the source of BDNF synthesis and secretion, and TFA promote endothelial dysfunction and therefore consequently lead to lower level of BDNF." (PMID 24199205, 2013). "Moreover, low-grade inflammatory status and endothelial dysfunction inhibit the expression of brain-derived neurotrophic factor (BDNF) because it is the endothelial cells that synthesize and secrete BDNF." (PMID 23286788, 2013). "Thus, it indicated that ANRIL mediated endothelial dysfunction through BDNF downregulation." (PMID 35906216, 2022). "Therefore, whether ANRIL can mediate endothelial dysfunction by BDNF regulation remains to be elucidated." (PMID 35906216, 2022). "Endothelial dysfunction is prevented by a high antioxidant diet, which is linked to reduced levels of pro-inflammatory cytokines in the plasma Moreover, pro-inflammatory cytokines like IL-6 and TNF- may also suppress BDNF expression." (PMID 34580389, 2021). "Whether circulating BDNF levels are associated with von Willebrand factor (vWF) levels, which are indicators of endothelial dysfunction is not known." (PMID 29409455, 2018). "Therefore, we hypothesized that endothelial dysfunction is an important factor for low circulating levels of BDNF in patients with CAD." (PMID 29409455, 2018). "A possible explanation for our finding is that TFA promote endothelial dysfunction and increase the production of pro-inflammatory cytokines that may interfere with neurotransmitter metabolism and inhibit Brain-derived neurotrophic factor (BDNF) expression among other physiological effects." (PMID 22047452, 2011). "Our results indicate that ANRIL directly binds to EZH2, and mediates BDNF promoter methylation through recruitment of EZH2 to the BDNF promoter region, eventually resulting in endothelial dysfunction." (PMID 35906216, 2022). "Our data have to be read taking into account that different processes, such as platelets activation, inflammation and endothelial dysfunction, typically present in CAD patients, can influence or be influenced by BDNF." (PMID 34205863, 2021). "Consistent with previous studies, in our study, serum BDNF levels were significantly decreased in CKD patients and the serum BDNF levels were correlated with eGFR positively, which suggested that it participated in the progression of CKD-related endothelial dysfunction." (PMID 35906216, 2022).
endothelial dysfunction (continued). "Meanwhile, BDNF upregulation could ameliorate endothelial and mitochondrial injury induced by ANRIL overexpression which indicated that ANRIL mediated endothelial dysfunction through BDNF, and these also verified its role in cardiovascular complications." (PMID 35906216, 2022). "Interestingly, endothelial dysfunction and blood–brain barrier (BBB) leakage induced by epileptic seizures may be the reason of decreased BDNF levels." (PMID 36807083, 2023). "However, it is important to note that different research works have showed that serum BDNF may not accurately reflect BDNF concentrations in the brain due to endothelial dysfunction." (PMID 31768951, 2020).
heart failure (36 papers, 2015 to 2025). Inability of the heart to pump blood at an adequate rate to meet tissue metabolic requirements. "Clinically, reduced circulating BDNF levels are associated with more advanced stages of heart failure and a worse prognosis." (PMID 41007658, 2025). "Accordingly, it has also been described that blood BDNF levels are associated with muscle strength and physical performance in patients with heart failure and in patients with haemodialysis." (PMID 39199297, 2024). "Compared with NT-proBNP, which is the most commonly used biomarker for the diagnosis and prognosis of heart failure patients, BDNF is also closely associated with the condition of heart failure patients." (PMID 38707889, 2024). "In a large population-based cohort study, low BDNF had association with high incidences of cardiovascular events including heart failure." (PMID 39728037, 2024). "The mechanism involved in the decreased circulating BDNF levels in heart failure is not well known, but it has been assumed that decreased heart cell mass is associated with reduced BDNF production." (PMID 36078878, 2022). "We further explored the association between BDNF and the established heart failure marker N-terminal pro b-type natriuretic peptide (NTproBNP)." (PMID 31659205, 2019). "Clinical observations showed that low blood BDNF levels are associated with a high risk of heart failure." (PMID 28178976, 2017). "Looking at the content related to volume status, the low levels of BDNF could modulate left atrial remodeling that leads to atrial fibrillation, the strong risk factor of heart failure." (PMID 39728037, 2024). "Furthermore, decreased circulating BDNF levels were linked to a worse clinical outcome in a study of individuals with CVDs such as angina pectoris or heart failure." (PMID 36741831, 2022). "Further, the gene encoding the receptor for BDNF is significantly up-regulated (n = 27, p = 0.002) in explants from patients with end-stage human heart failure, compared to unused donor healthy heart controls (n = 16), perhaps as a compensatory response to reduced BDNF levels." (PMID 33050457, 2020). "Furthermore, the association of blood BDNF levels with cardiovascular diseases, such as angina pectoris and heart failure were reported, with lower levels of BDNF being associated with the risk of cardiovascular diseases." (PMID 28178976, 2017). "In a rat model of heart failure, Sirt1 expression was reduced, while NF-κB p65 and miR-155 were found to be upregulated, and BDNF was downregulated, which contributed to cardiac dysfunction and increased apoptosis." (PMID 41226851, 2025). "Studies examining myokines such as irisin and Brain-Derived Neurotrophic Factor (BDNF) on heart failure have demonstrated that the beneficial effects of myokines are mediated through the activation of the AMPKα-PGC1α signaling pathway." (PMID 41141371, 2025). "Sirt1 has a protective function in heart failure by modulating the NF-κB p65/miR-155/BDNF signaling pathway." (PMID 41226851, 2025). "It has been shown that serum brain-derived neurotrophic factor (BDNF) is associated with skeletal muscle energy metabolism and that BDNF is a predictor of mortality in heart failure patients." (PMID 38319936, 2024). "The known myokines related to heart failure originating from skeletal muscle are primarily decorin, irisin, myonectin, brain-derived neurotrophic factor (BDNF), growth differentiation factor-11 (GDF-11), myostatin, and osteonectin." (PMID 39203852, 2024). "BDNF is involved in endogenous myocardial repair and regulation of myocardial contractility in heart failure patients." (PMID 38707889, 2024). "Lower BDNF levels were observed in patients with heart failure compared with healthy controls, especially in patients with a history of severe cardiovascular disease." (PMID 38137853, 2023). "As in the general population, lower circulating BDNF levels negatively affected clinical outcomes in patients with angina pectoris or heart failure." (PMID 36741831, 2022).